ATP4A (ATPase H+/K+ transporting subunit alpha)
Description:
The catalytic subunit of the gastric H(+)/K(+) ATPase pump which transports H(+) ions in exchange for K(+) ions across the apical membrane of parietal cells. Uses ATP as an energy source to pump H(+) ions to the gastric lumen while transporting K(+) ion from the lumen into the cell (By similarity). Remarkably generates a million-fold proton gradient across the gastric parietal cell membrane, acidifying the gastric juice down to pH 1 (By similarity). Within a transport cycle, the transfer of a H(+) ion across the membrane is coupled to ATP hydrolysis and is associated with a transient phosphorylation that shifts the pump conformation from inward-facing (E1) to outward-facing state (E2). The release of the H(+) ion in the stomach lumen is followed by binding of K(+) ion converting the pump conformation back to the E1 state (By similarity).
Synonyms: ATP6A
Tractability: Small molecule: an approved drug acts on it; it belongs to a druggable protein family. Antibody: UniProt places it where antibodies can reach, with high confidence; its Gene Ontology location is reachable by antibodies, with high confidence; UniProt predicts a signal peptide or a membrane-spanning region. PROTAC: ubiquitination databases record sites on it; a small molecule that binds it is known.
Gene: Protein-coding gene on chromosome 19 (35,550,031 to 35,563,658, reverse strand). Ensembl gene ENSG00000105675.
Subcellular location: Apical cell membrane
Pathways (Reactome):
Transport of small molecules: Ion transport by P-type ATPases
Gene Ontology:
Molecular function: magnesium ion binding; P-type potassium:proton transporter activity; P-type sodium:potassium-exchanging transporter activity; potassium ion binding; ATP binding; ATP hydrolysis activity; nucleotide binding; P-type potassium transmembrane transporter activity
Biological process: intracellular potassium ion homeostasis; intracellular sodium ion homeostasis; monoatomic ion transmembrane transport; potassium ion import across plasma membrane; proton transmembrane transport; sodium ion export across plasma membrane; establishment or maintenance of transmembrane electrochemical gradient; potassium ion transport
Cellular component: apical plasma membrane; extracellular region; plasma membrane; membrane
Genetic constraint (gnomAD): Loss-of-function variants: 73 observed, 109.74 expected, observed/expected ratio (o/e) 0.67, 90% interval 0.55 to 0.81. The upper end of that interval is the gene's LOEUF score, 0.81, which puts it in group 3 of 6, group 1 being the genes least tolerant of losing a copy. Missense variants: 1,081 observed, 1,442 expected, observed/expected ratio (o/e) 0.75, 90% interval 0.71 to 0.79. Synonymous variants: 588 observed, 601.99 expected, observed/expected ratio (o/e) 0.98, 90% interval 0.91 to 1.05.
Homologues: Orthologues: macaque ATP4A (99% identical), chimpanzee ATP4A (99% identical), pig ATP4A (98% identical), mouse Atp4a (98% identical), dog ATP4A (98% identical), rat Atp4a (98% identical), rabbit ATP4A (97% identical), guinea pig ATP4A (96% identical), tropical clawed frog atp4a (85% identical), Caenorhabditis elegans catp-3 (36% identical), Caenorhabditis elegans catp-2 (35% identical), Drosophila melanogaster SPoCk (24% identical), and 6 more. Paralogues in human: ATP12A (64% identical), ATP1A3 (63% identical), ATP1A1 (62% identical), ATP1A2 (62% identical), ATP1A4 (59% identical), ATP2A2 (28% identical), ATP2A3 (27% identical), ATP2A1 (27% identical), ATP2B2 (27% identical), ATP2B3 (27% identical), ATP2B1 (26% identical), ATP2B4 (26% identical), and 9 more.
Diseases named in the same sentence as ATP4A in open-access papers:
ATP4A is named in the same sentence as 39 diseases in open-access papers, as found by Europe PMC text mining. Sharing a sentence is not in itself a finding about the gene and the disease. The quoted sentences say what the papers report.
gastric cancer (12 papers, 2018 to 2025). A primary or metastatic malignant neoplasm involving the stomach. "Of note, the down-regulation of ATP4A or ATP4B expression has been associated with gastric cancer prognosis." (PMID 35741779, 2022). "Atp4a had a strong positive linear correlation with ghrl (among survival genes), and both of them were underexpressed in gastric cancer according to GEPIA boxplot, which resulted in gastric acid secretion downregulation." (PMID 35650297, 2022). "In conclusion, three hub genes (ATP4A, ATP4B, and ESRRG) closely related to gastric cancer were mined, based on which the ML diagnostic model of gastric cancer was conducted." (PMID 35812327, 2022). "The expression level of ATP4a, a differentiation-related gene, was significantly downregulated in gastric cancer tissues, and the methylation level of the gene body was negatively correlated with the expression of ATP4a." (PMID 36443876, 2022). "Here we showed that the phenotypic progression to IM observed in the Atp4a−/− mouse model is similar to the evolution of gastric cancer in humans, as initially described by Correa." (PMID 31904088, 2020). "We identified REG1A, CHGA, TFF2, ATP4A and ATP4B to be downregulated in intestinal gastric cancer, and Rajkumar and co-workers found ATP4A and ATP4B to be downregulated in gastric tumor tissues compared to normal tissues." (PMID 29484116, 2018). "The results showed that 8 up-regulated genes (FN1, COL3A1, FBN1, BGN, COL5A2, THBS2, COL5A1 and SPARC) and 1 down-regulated gene (ATP4A) may be the central genes in gastric cancer." (PMID 32742441, 2020). "Long-term treatment of PPIs has been reported to lead to gastric carcinoma, and the carcinogenic effect of lack of function of the proton pump is also shown in the family with ATP4A mutation." (PMID 33266504, 2020). "Therefore, ghrl and possibly atp4a have a protective role in gastric cancer." (PMID 35650297, 2022). "Meanwhile, ATP4A and ATP4B downregulation involve DNA methylation and methylated ATP4B DNA in the plasma are potential biomarkers for gastric cancer." (PMID 32596394, 2020). "The areas under the curve (AUCs) were 0.7786 and 0.7496 for ATP4A and ATP4B mRNA, respectively (95% CI, 0.6885‒0.8687 and 0.6452‒0.8540, respectively), suggesting its potential utility as a biomarker for gastric cancer." (PMID 41114471, 2025). "GRA had a demethylation effect on ATP4a in vivo and in vitro, activating the expression of ATP4a and inhibiting the occurrence of gastric cancer, suggesting that GRA is an effective demethylating agent with certain clinical application prospects for the treatment of gastric cancer." (PMID 36443876, 2022).
atrophic gastritis (5 papers, 2016 to 2024). "Genetically mediated ATP4a mutation induced gastric atrophy and H. pylori induced gastric atrophy therefore seem to alter mitochondrial function through similar mechanisms, but these are different from those found in classical autoimmune atrophic gastritis." (PMID 35059996, 2022). "Variations in the pathology of atrophic gastritis have been reported to some degree in genetically engineered mice such as Atp4a−/− and gastrin−/− mice, which are used as models of parietal and glandular cell loss." (PMID 26839577, 2016). "Our previous studies uncovered alterations in the ATPase H+/K+ Transporting Subunit Alpha (ATP4A) proton pump that triggered an internal cell acid–base imbalance, offering an autoimmune scenario for atrophic gastritis and gastric neuroendocrine tumors with secondary autoimmune pathologies." (PMID 34944008, 2021). "Therefore, we concluded that the Atp4a−/− mouse is an excellent model with which to study the development of gastric IM from atrophic gastritis." (PMID 31904088, 2020).
gastric NETs (4 papers, 2016 to 2026). "Rare hereditary cases carrying germline ATP4A mutations develop gastric neuroendocrine tumors and adenocarcinoma at young age." (PMID 41493925, 2026). "GEMMs that carry an Atp4a mutation that has been found in patients with familial gastric NETs recapitulate hypergastrinemia and develop gastric NETs." (PMID 29590641, 2018). "The recessive mutation found in the ATP4a gene (p.R703C) responsible for atypical type I familial gastric NETs corresponds to the p.R702C mutation in mice." (PMID 27491072, 2016).
pancreatic cancer (4 papers, 2015 to 2020). "We observed differential methylation of FOSB, KLF6, ATP4A, and GSG1 genes that are previously reported as markers for pancreatic cancer survival." (PMID 28423671, 2017). "We also observed the differential methylation of four pancreatic cancer marker genes, i.e., FOSB, KLF6, ATP4A, GSG1, related to survival of patients." (PMID 28423671, 2017). "Furthermore, our recent data mining analyses indicate that on the mRNA level ATP4A and ATP4B are down-regulated in pancreatic cancer." (PMID 25993003, 2015).
anemia (3 papers, 2016 to 2024). A reduction in the number of red blood cells, the amount of hemoglobin, and/or the volume of packed red blood cells. "In summary, KI/KI mice mimic all biochemical features of human individuals homozygous for the ATP4a gene mutation (achlorhydria, hypergastrinemia and iron-deficiency anemia)." (PMID 27491072, 2016). "Finally, a missense mutation in ATP4A was described to be responsible for a microcytic hypochromic anemia in a sublityc mouse model." (PMID 35208164, 2022). "Increased ATP4A and ATP4B antibody levels were found in patients with PCAs and in subjects with a clinical suspicion of gastric body atrophy (presence of dyspepsia, anemia, and histological findings of a concomitant Helicobacter pylori infection)." (PMID 39202208, 2024).
gastric tumor (2 papers, 2018 to 2025). "A recent experimental study further demonstrated that the reactivation of ATP4A through intragenic DNA demethylation effectively suppressed gastric tumor growth, indicating a direct epigenetic mechanism contributing to its silencing and therapeutic reactivation." (PMID 40725485, 2025).
atrial fibrillation (1 paper, 2013). A disorder characterized by an electrocardiographic finding of a supraventricular arrhythmia characterized by the replacement of consistent P waves by rapid oscillations or fibrillatory waves that vary in size, shape and timing and are accompanied by an irregular ventricular response. "We demonstrate the use of our algorithm to predict novel candidate genes for human atrial fibrillation (such as HRH2, ATP4A, ATP4B, and HOPX) and epilepsy (e.g., PAX6 and NKX2-1)." (PMID 23800157, 2013).
autoimmune gastritis (1 paper, 2023). Inflammation of the body fundic mucosa of the stomach. "Researchers have developed luciferase immunoprecipitation assays targeting ATP4A and ATP4B and have demonstrated favorable diagnostic accuracy in patients with histologically confirmed autoimmune gastritis." (PMID 37504250, 2023).
cyst (1 paper, 2020). A sac-like closed membranous structure that may be empty or contain fluid or amorphous material. "In addition to the increased number of cells per gland and cyst formation, a wide variety of hyperplastic and metaplastic cells developed in aged Atp4a–/– mice." (PMID 31904088, 2020).
gastric disease (1 paper, 2021). "Here, we have described four new variants in the ATP4A gene in 46.7% and 13.3% of the studied patients with gNETs and CAG, respectively, which demonstrates not only the role of this gene in gastric disease but also its correlation with disease severity." (PMID 34944008, 2021).
Graves disease (1 paper, 2021). Graves' disease is an autoimmune disorder that leads to overactivity of the thyroid gland (hyperthyroidism).It is caused by an abnormal immune system response that causes the thyroid gland to produce too much thyroid hormones. "In the thyroid, ATP4A and PTH2R variants were only found in Hashimoto’s disease, while SLC9A4 variants were only found in Graves’ disease." (PMID 34944008, 2021).
hypopharyngeal carcinoma (1 paper, 2022). Carcinoma, predominantly squamous cell, arising from the epithelial cells of the hypopharynx. "Hypopharyngeal carcinoma FaDu cells expressing H+/K+-ATPase α, β (ATP4A and ATP4B) induced mitochondrial damage and the expression of related genes." (PMID 35083516, 2022).
inflammatory bowel disease (1 paper, 2021). A spectrum of small and large bowel inflammatory diseases of unknown etiology. "The inflammatory bowel disease described in the F1 family affected with gNETs caused by ATP4A mutations fits in this scenario." (PMID 34944008, 2021). "Recently, co-occurring colitis compatible with inflammatory bowel disease was observed in the follow-up of these ATP4A malfunction-mediated gNET patients), which suggested a common genetic origin of two immunodeficiencies of different etiology." (PMID 34944008, 2021).
insulinomas (1 paper, 2023). "The knock-down of ATP4A in the insulinoma cell line MIN6 led to decreased glucose-stimulated insulin secretion." (PMID 37772258, 2023). "ROC curves with areas under the curve (AUC) are shown for investigating the diagnostic effectiveness of the nomogram model between insulinoma and NFPNET by using the identified three target genes (ATP4A, MCOLN1, and ATP6V0E1)." (PMID 37772258, 2023). "In summary, these outcomes suggest that ATP4A, MCOLN1, and ATP6V0E1 are crucially ion channel-related genes in insulinoma, and the diagnostic model based on these genes was highly efficient." (PMID 37772258, 2023). "In summary, MCOLN1, ATP6V0E1, and ATP4A might enhance the insulin secretion of insulinomas by participating in regulating the function and TGF-beta signaling pathway." (PMID 37772258, 2023). "Since ATP4A, MCOLN1, and ATP6V0E1 might be pivotal in the ion channels for insulinoma and participate in regulating the secretion of various hormones, we selected these three target genes separately for further single-gene GSEA and GSVA analyses." (PMID 37772258, 2023). "Exploring potential therapeutic drugs for targeting ATP4A, MCOLN1, and ATP6V0E1 might offer a definite treatment approach to symptom improvement of insulinoma." (PMID 37772258, 2023).
liver disease (1 paper, 2017). "Atp4aSl/Sl mice developed more severe ethanol-associated liver disease than littermates with wild-type Atp4a (WT)." (PMID 29038503, 2017).
maturity onset diabetes (1 paper, 2025). "Additional pathways included maturity onset diabetes (NEUROD1 gene), collecting duct acid secretion (ATP4A), and various metabolic processes." (PMID 40725485, 2025).
thyroid disease (1 paper, 2021). "Cotransporter genes involved in achlorhydria (SLC26A7, SLC26A9 and ATP4A) were also strongly associated with thyroid disease in thyrogastric patients, suggesting a monogenic model for the thyrogastric syndrome." (PMID 34944008, 2021).
viral infections (1 paper, 2021). "However, we recently demonstrated the relevance of mutations in the ATP4A gene in achlorhydria and its importance for CAG, gNETs and derived secondary viral infections." (PMID 34944008, 2021).
tumor (11 papers, 2013 to 2026). "ATP4A is a pivotal tumor suppressor gene that encodes H+, K+-ATPase, which mediates gastric acid secretion in the stomach." (PMID 40519260, 2025). "ATP4a is an important tumor suppressor gene, encoding H+, K+-ATPase, and there is an inverse correlation between methylation and expression in ATP4a." (PMID 36523499, 2022). "In conclusion, the present study found that the Atp4a–/– mouse appeared to provide an excellent model for studying severe glandular hyperplasia, hyaline transformation and IM, as well as the up-regulation of many factors related to cell proliferation and tumor development." (PMID 31904088, 2020). "Both these genes were oncogenes, and downregulated genes such as ATP4A, ATP4B, PGA3, PGA4, and PGA5 were reported tumor suppressors in GC." (PMID 39283078, 2024). "We observed that the expressions of ESSRG, ATP4A, and ATP4B in tumor samples were significantly lower than those in normal ones." (PMID 35812327, 2022). "ATP4A was highly expressed in the adjacent normal group yet not expressed in the tumor group." (PMID 39886652, 2025).
infection (3 papers, 2013 to 2017). The state of being infected such as from the introduction of a foreign agent such as serum, vaccine, antigenic substance or organism. "We observed downregulation of Atp4a and Atp4b in response to infection with H. felis, which may represent a loss of parietal cells that has been shown to precede gastric dysplasia." (PMID 28201999, 2017). "In addition to the immunofluorescent staining, the transcriptional analysis of parietal cell markers shows that ATP4A and AQP4 were significantly down regulated following a trickle infection, whereas KCNQ1 transcript levels were unchanged in all animals." (PMID 24330735, 2013).
ATP4A also shares sentences with these, for which no sentence is quoted: cancer (5 papers); Acidosis (1); adenocarcinoma (1); Crohn disease (1); dyspepsia (1); epilepsy (1); gastrointestinal disease (1); Hashimoto’s disease (1); HCMV infection (1); Iron deficiency anemia (1); laryngeal carcinoma (1); Leigh syndrome (1); lung carcinoma (1); metabolic dysfunction-associated steatohepatitis (1); metabolic dysfunction-associated steatotic liver disease (1); metastatic disease (1); primary biliary cirrhosis (1); respiratory system disease (1); Sjogren syndrome (1).